NEFL (neurofilament light chain)
Description:
Neurofilaments usually contain three intermediate filament proteins: NEFL, NEFM, and NEFH which are involved in the maintenance of neuronal caliber. May additionally cooperate with the neuronal intermediate filament proteins PRPH and INA to form neuronal filamentous networks (By similarity).
Synonyms: NF-L; NF68; NFL; CMT1F; CMT2E; PPP1R110; CMTDIG
Tractability: PROTAC: UniProt records ubiquitination sites on it; ubiquitination databases record sites on it; its protein half-life has been measured.
Gene: Protein-coding gene on chromosome 8 (24,950,955 to 24,956,721, reverse strand). Ensembl gene ENSG00000277586.
Subcellular location: Cell projection, axon; Cytoplasm, cytoskeleton
Subcellular location (Human Protein Atlas): Intermediate filaments; Nucleoplasm; Midbody
Pathways (Reactome):
Neuronal System: Assembly and cell surface presentation of NMDA receptors; Long-term potentiation; Negative regulation of NMDA receptor-mediated neuronal transmission; Ras activation upon Ca2+ influx through NMDA receptor; Unblocking of NMDA receptors, glutamate binding and activation
Signal Transduction: RAF/MAP kinase cascade
Gene Ontology:
Molecular function: identical protein binding; protein binding; structural constituent of cytoskeleton; tubulin binding; protein-macromolecule adaptor activity; structural constituent of postsynaptic intermediate filament cytoskeleton; phospholipase binding; protein domain specific binding; protein-containing complex binding
Biological process: anterograde axonal transport; axonal transport of mitochondrion; intermediate filament organization; neurofilament bundle assembly; retrograde axonal transport; cerebral cortex development; hippocampus development; intermediate filament polymerization or depolymerization; postsynaptic intermediate filament cytoskeleton organization; postsynaptic modulation of chemical synaptic transmission; protein polymerization; regulation of synapse maturation; response to acrylamide; response to corticosterone; response to peptide hormone; response to sodium arsenite; response to toxic substance; spinal cord development
Cellular component: axon; neurofilament; cytoplasm; cytosol; intermediate filament; postsynaptic intermediate filament cytoskeleton; axon cytoplasm; cholinergic synapse; cytoskeleton; growth cone; intermediate filament cytoskeleton; neuromuscular junction; neuron projection; presynaptic intermediate filament cytoskeleton; Schaffer collateral - CA1 synapse
Genetic constraint (gnomAD): Loss-of-function variants: 36 observed, 48.23 expected, observed/expected ratio (o/e) 0.75, 90% interval 0.57 to 0.99. The upper end of that interval is the gene's LOEUF score, 0.99, which puts it in group 4 of 6, group 1 being the genes least tolerant of losing a copy. Missense variants: 646 observed, 692.56 expected, observed/expected ratio (o/e) 0.93, 90% interval 0.87 to 1. Synonymous variants: 322 observed, 304.02 expected, observed/expected ratio (o/e) 1.06, 90% interval 0.97 to 1.16.
Gene-disease validity (ClinGen):
ClinGen rates the evidence that NEFL causes each of these diseases.
Charcot-Marie-Tooth disease (autosomal dominant): Definitive. An inherited degenerative disorder involving the peripheral nerves.
Charcot-Marie-Tooth disease type 2 (autosomal recessive): Definitive. A Charcot-Marie-Tooth disease characterized by abnormalities in the axon of the peripheral nerve cell.
Homologues: Orthologues: chimpanzee NEFL (100% identical), macaque NEFL (99% identical), dog NEFL (99% identical), guinea pig NEFL (98% identical), rat Nefl (96% identical), mouse Nefl (96% identical), pig NEFL (89% identical), rabbit NEFL (88% identical), tropical clawed frog nefl (71% identical), zebrafish neflb (56% identical). Paralogues in human: NEFM (45% identical), INA (43% identical), PRPH (37% identical), DES (37% identical), VIM (36% identical), GFAP (33% identical), KRT73 (26% identical), KRT8 (26% identical), KRT72 (25% identical), KRT75 (24% identical), KRT84 (24% identical), KRT5 (24% identical), and 56 more.
Diseases named in the same sentence as NEFL in open-access papers:
NEFL is named in the same sentence as 481 diseases in open-access papers, as found by Europe PMC text mining. Sharing a sentence is not in itself a finding about the gene and the disease. The quoted sentences say what the papers report.
Alzheimer disease (363 papers, 2005 to 2026). A progressive, neurodegenerative disease characterized by loss of function and death of nerve cells in several areas of the brain leading to loss of cognitive function such as memory and language. "Neurofilament Light Chain (NfL): NfL, a marker of neurodegeneration in Alzheimer's disease, has shown a strong association with cognitive decline." (PMID 39377784, 2025). "Neurofilament light chain, glial fibrillary acidic protein and phosphorylated-tau 181 levels were elevated in early-onset Alzheimer’s disease compared with other diagnostic categories." (PMID 39825484, 2025). "Levels of neurofilament light chain, glial fibrillary acidic protein and phosphorylated-tau 181, apolipoprotein E genotype and late-onset Alzheimer’s disease polygenic risk scores were determined." (PMID 39825484, 2025). "Plasma levels of protein biomarkers glial fibrillary acidic protein (GFAP) and neurofilament light (NEFL) are key dementia biomarkers, but it is unclear how risk genes for Alzheimer’s disease (AD) influence levels of these biomarkers." (PMID 40061357, 2025). "We examined the bivariate relationships of WMH, amyloid beta 42/40, phosphorylated tau 217 and glial fibrillary acidic protein with age-residualized neurofilament light chain across Alzheimer’s disease diagnostic groups." (PMID 39403075, 2024). "Synaptosomal-associated protein 25 kDa and neurofilament light chain were increased in mild cognitive impairment and Alzheimer’s disease patients." (PMID 37680670, 2023). "Neurofilament light chain (NfL) is a potential diagnostic and prognostic plasma biomarker for numerous neurological diseases including Alzheimer’s disease (AD)." (PMID 38139190, 2023). "Recently, significant aberration in neurofilament light chain (NfL) levels have been associated with Alzheimer’s disease (AD), amyotrophic lateral sclerosis, multiple sclerosis and cerebral vascular disease." (PMID 34768602, 2021). "The neurofilament light chain (NfL), a component of the axonal cytoskeleton, has been identified as a marker of neuro-axonal damage in various neurological disorders, including Alzheimer’s disease." (PMID 39944951, 2025). "Neurofilament light chain (NfL), a sensitive marker of neuronal injury, has emerged as a potential biomarker in various neurodegenerative and neuroinflammatory conditions, such as Alzheimer’s disease (AD), Parkinson’s disease (PD), multiple sclerosis (MS)." (PMID 40988756, 2025). "Protein Tau, neurofilament light chain (NfL), and amyloid β are leading biomarkers for diagnosing Alzheimer’s disease in its early stages." (PMID 41373474, 2025). "These discoveries from ELSA were robustly replicated in the UKB, where NEFL, MMP12, KIM1 and EDA2R were significantly associated with ACD, Alzheimer’s disease and VAD." (PMID 40092369, 2025). "Cerebrospinal fluid (CSF) total tau (t-tau) is considered a biomarker of neuronal degeneration alongside brain atrophy and fluid neurofilament light chain protein (NfL) in biomarker models of Alzheimer’s disease (AD)." (PMID 40883301, 2025). "The improper homeostasis of fatty-acid-binding proteins (FABPs), glutamic acid (GA), and neurofilament light chain (NFL) have been suggested in the pathogenesis of Alzheimer’s disease (AD), Parkinson’s disease, and other NDs." (PMID 38337350, 2024). "We observed elevated neurofilament light chain in preclinical Alzheimer’s disease plasma for two measures (NfL101 and NfL324) and CSF for seven measures (NfL92, NfL101, NfL117, NfL137, NfL148, NfL165 and NfL530)." (PMID 39165480, 2024). "Common biomarkers include cerebrospinal fluid (CSF) tau and amyloid-beta levels, which are primarily used in Alzheimer’s disease (AD), and the neurofilament light chain (NfL), a marker for neuronal damage across various neurodegenerative conditions." (PMID 39337696, 2024).
Alzheimer disease (continued). "They found that profiles of neurofilament light chain differ in CSF and plasma and that different peptides in CSF and plasma separate amyloid groups in preclinical and mild Alzheimer’s disease." (PMID 39165480, 2024). "Plasma neurofilament light chain (NfL) is a blood biomarker of neurodegeneration, including Alzheimer’s disease." (PMID 39267169, 2024). "Plasma neurofilament light chain (NFL) is a biomarker of inflammation and neurodegenerative diseases such as Alzheimer's disease (AD)." (PMID 37545369, 2023). "Neurofilament light chain (NF-L), a neuronal cytoplasmic protein used as a marker for amyotrophic lateral sclerosis, multiple sclerosis, Alzheimer’s disease and Huntington’s disease monitoring." (PMID 36831830, 2023). "Neurofilament light chain (NfL) is an emerging blood biomarker to evaluate neuroaxonal damage such as Alzheimer’s disease, multiple sclerosis, postoperative delirium, multiple system atrophy, and amyotrophic lateral sclerosis." (PMID 37817286, 2023). "Background and Objectives: The neurofilament light chain (NfL) is a biomarker for neuro-axonal injury in various acute and chronic neurological disorders, including Alzheimer’s disease (AD)." (PMID 35334608, 2022). "Potential biomarkers for Alzheimer’s disease (AD) include amyloid β1–42 (Aβ1–42), t-Tau, p-Tau181, neurofilament light chain (NFL), and neuroimaging biomarkers." (PMID 35052848, 2022). "Plasma biomarkers, including tau, neurofilament light chain (NfL) and Aβ are increasingly being used to define and stage Alzheimer’s disease." (PMID 35221998, 2022). "NfL324 [neurofilament light chain tryptic peptide GMNEALEK (NfL amino acids 324–331)] was 1.5-fold increased in Alzheimer’s disease compared with control (P = 0.001) and NfL530 was 1.7-fold increased (P = 0.0001)." (PMID 35415607, 2022). "There is also an extensive literature demonstrating the predictive utility of standard Alzheimer’s disease biomarkers (e.g. amyloid-β42, tau, neurofilament light chain) among CN older adults for progression to MCI or Alzheimer’s disease." (PMID 34396116, 2021). "The measurement of neurofilament light chain (NfL) levels is emerging as a promising biomarker for the monitoring and management of neurodegenerative diseases, such as Alzheimer’s disease, MS, and Parkinson’s disease." (PMID 32932824, 2020). "CSF neurofilament light chain (NfL), which is a marker of axonal injury, is increased in a broad spectrum of neurological disorders and also in Alzheimer′s disease (AD), frontotemporal dementia, and vascular dementia." (PMID 33198266, 2020). "However, we did not observe correlations between BAG and cerebrospinal fluid markers of Alzheimer’s dementia, neurofilament light chain, or uptake ratios extracted from DaTSCAN analysis at baseline, indicating that BAG provides an independent biomarker." (PMID 41361244, 2025). "Blood‐based phosphorylated tau 217 (p‐tau217), glial fibrillary acidic protein (GFAP), and neurofilament light chain (NfL) show promise for Alzheimer's disease (AD), while their links to brain amyloid beta (Aβ)/tau, hippocampal atrophy, and cognitive decline need further investigation." (PMID 41376134, 2025). "Elevated serum neurofilament light chain (sNfL) levels in patients with multiple sclerosis, Alzheimer’s disease, Parkinson’s and Huntington’s diseases, motor neuron diseases, cerebrovascular accidents, hereditary peripheral neuropathies, and impairments associated with traumatic brain injury." (PMID 40689320, 2025). "What is the clinical value of blood-based biomarkers (plasma phosphorylated tau217 [p-tau217], glial fibrillary acidic protein [GFAP], and neurofilament light chain [NfL]) to detect Alzheimer disease (AD) in clinical syndromes related to frontotemporal lobar degeneration (FTLD)?" (PMID 39928343, 2025).
Alzheimer disease (continued). "For instance, neurofilament light chain (NfL) has emerged as a robust biomarker of neurodegeneration, providing valuable insights into disease progression in Alzheimer’s disease (AD), Parkinson’s disease (PD), multiple sclerosis (MS), and amyotrophic lateral sclerosis (ALS)." (PMID 40076852, 2025). "In particular, NEFL has been reported to be a biomarker of Alzheimer disease, where CD33 may drive impaired phagocytic capacity of microglia and pose a risk for Alzheimer's disease." (PMID 37506557, 2023). "Neurofilament light chain (NFL) level is another indicator of axonal damage that presents a significant increase in the plasma of Alzheimer’s disease patients and in other neurodegenerative disorders; therefore, it consists of another sensitive but not specific biomarker." (PMID 36009425, 2022). "In this study, we investigated the diagnostic performance of plasma GFAP (pGFAP), plasma neurofilament light chain (pNfL) and their combination for frontotemporal dementia (FTD) and Alzheimer’s disease (AD) and their clinical utility in predicting disease progression." (PMID 34893073, 2021). "A growing body of evidence suggests that the plasma concentration of the neurofilament light chain (NfL) might be considered a plasma biomarker for the screening of neurodegeneration in Alzheimer’s disease (AD)." (PMID 30055655, 2018). "Neurofilament light chain (NfL) is a neuronal cytoskeletal protein that has been investigated as a molecular marker of neurodegeneration in the context of numerous neurodegenerative diseases, including Alzheimer's disease, amyotrophic lateral sclerosis, and multiple sclerosis, among others." (PMID 39998458, 2025). "This study supports neurofilament light chain protein (NfL) in both cerebrospinal fluid (CSF) and blood as an early marker of neurodegeneration in Alzheimer’s disease but suggests that NfL in CSF may be better suited than blood for monitoring clinical trial outcomes in symptomatic patients." (PMID 39557867, 2024). "In other neurological disorders, including Multiple Sclerosis (MS), Alzheimer's disease (AD), and Parkinson's disease (PD), neurofilament light chain levels (NfL) in body fluids such as serum, plasma or CSF may provide a biomarker for tracking disease activity including progression." (PMID 33737864, 2021). "Neurofilament light chain (NfL) and glial fibrillary acidic protein (GFAP) are detected in blood samples from a variety of neurodegenerative conditions including late-onset Alzheimer’s disease, Lewy body disease and frontotemporal dementia." (PMID 39825484, 2025). "Neurofilament Light Chain (NfL) is a biomarker of axonal injury elevated in mild cognitive impairment (MCI) and Alzheimer’s disease dementia." (PMID 38757180, 2025). "Secondary endpoints were Clinical Dementia Rating (CDR) plus National Alzheimer’s Disease Coordinating Center (NACC) Frontotemporal Lobar Degeneration (FTLD) rating scale and levels of neurofilament light chain (NfL)." (PMID 38745011, 2024). "In another study, researchers revealed that CSF Ng, neurofilament light chain (NfL), and YKL-40 were increased in Alzheimer’s disease." (PMID 39769345, 2024). "The novel amyloid-beta, p-Tau, and neurofilament light chain (ATN) classification scheme has become a promising system for clinically detecting and diagnosing Alzheimer's disease (AD)." (PMID 39822440, 2024). "This study aimed to evaluate the use of serum neurofilament light chain (NfL) and glial fibrillary acidic protein (GFAP) in the diagnosis of Alzheimer’s disease (AD) and the differential diagnosis between AD and mild cognitive impairment (MCI)." (PMID 38352136, 2024). "NEFL and TIMP4 were also consistently dysregulated in all types of dementia in a PEA-based study in the Massachusetts Alzheimer’s Disease Research Center cohort." (PMID 37175824, 2023).
Alzheimer disease (continued). "Compared to those with late-onset Alzheimer’s disease, patients with early-onset Alzheimer’s disease presented more severe impairment in language function, lower frequency of APOE ɛ4 and lower levels of plasma neurofilament light chain (all P < 0.05)." (PMID 39850631, 2025). "Similarly, cognitive performance in Alzheimer's disease and amyloid PET status can be predicted and classified by a combination of GFAP, amyloid beta, and neurofilament light chain." (PMID 38234075, 2024). "In the present study, we evaluated how plasma p‐tau181, GFAP, and a marker of neurodegeneration (neurofilament light chain; NfL) differed by clinical diagnosis and related to Aβ‐PET in Hispanic and non‐Hispanic older adults from the 1Florida Alzheimer's Disease Research Center (1FLADRC)." (PMID 37671801, 2024). "For example, the up-regulated levels of neurofilament light chain (NFL) and glial fibrillary acidic protein (GFAP) in serum may indicate neuronal damage in the progression of neurodegenerative diseases, such as Alzheimer’s disease or Parkinson’s disease." (PMID 36744129, 2023). "Serum neurofilament light chain (S NfL) is a non-specific marker of neuronal damage, including Alzheimer’s disease (AD)." (PMID 38164192, 2023). "Plasma neurofilament light chain (NfL) is a novel biomarker for neurodegenerative diseases, such as Alzheimer’s disease (AD), but it has not been measured in patients with cancers, such as gastric cancer (GC)." (PMID 32082140, 2020). "Blood markers indicative of neurodegeneration (neurofilament light chain; NFL), Alzheimer’s disease amyloid pathology (amyloid-β; Aβ), and neuroinflammation (kynurenine pathway; KP metabolites) have been investigated independently in neurodegenerative diseases." (PMID 31601232, 2019). "The possibility of increased protein synthesis has been ruled out in degenerating neurons of ALS and Alzheimer disease patients in which NEFL mRNA levels are downregulated, whereas the transcript levels for NEFM or NEFH usually remain unchanged." (PMID 27021905, 2016). "We investigated whether CSF concentrations of neurofilament light chain (NFL), soluble amyloid-β protein precursor α (sAβPPα), sAβPPβ, and CSF/serum albumin ratio could separate SSVD from healthy controls, Alzheimer’s disease (AD), and mixed dementia (combined AD and SSVD)." (PMID 37980667, 2023). "Thus, for example, cerebrospinal fluid (CSF) and blood levels of the neurofilament light chain (NfL) have been used as a sensitive biomarker for neuroaxonal damage that can monitor neurodegeneration and progression of Alzheimer’s disease dementia, albeit not specific." (PMID 36685284, 2022). "Likewise, the inclusion of a plasma-based neurodegeneration biomarker such as plasma neurofilament light chain, while not specific for Alzheimer’s disease, may also improve prognostic capacity." (PMID 34222875, 2021).